HIF1A (hypoxia inducible factor 1 subunit alpha)
Diseases named in the same sentence as HIF1A in open-access papers (continued):
Sharing a sentence is not in itself a finding about the gene and the disease.
cancer (continued). "Alterations of VHL lead to impaired degradation of hypoxia-inducible factor 1α (HIF1α) and HIF2α promoting neoangiogenesis, which is pivotal for cancer growth." (PMID 39858553, 2024). "An example of a cancer-associated regulator of glycogen is the oncogene RAB25 gene, which up-regulates HIF-1α activity in an oxygen-independent manner, and HIF-1α and hypoxia are shown to enhance glycogen concentration." (PMID 39479019, 2024). "Our concept and the data presented here indicated that SP1, MYC, and HIF1A were the missing links between miRNAs and cancer stem cells." (PMID 39590335, 2024). "As the understanding of HIF-1α’s role in cancer biology expands, further investigation into innovative combination therapies and delivery methods will be essential to optimize patient outcomes and advance the field of oncology." (PMID 39493156, 2024). "Based on this observation, we examined the expression profile of Arg1 and HIF1a by mIF imaging in the same ROIs employed for the analysis of the colocalization of Krt8+ cancer cells, CD31+ vasculature, and Col1 1+ protein fibers." (PMID 39372930, 2024). "The downstream transcription factors of the mTOR signaling pathway (with the highest enrichment score) include HIF1α, c-Myc, FoxO, and other important cancer regulatory molecules." (PMID 38418940, 2024). "By modulating alpha-ketoglutarate (α-KG) and succinate levels, P4HA1 expression reduces proline hydroxylation on HIF-1α, enhancing its stability in cancer cells." (PMID 38544822, 2024). "In the cancer cell, pVHL acts as a target recruitment subunit in the E3 ubiquitin ligase complex and recruits hydroxylated HIF-1α under normoxic conditions." (PMID 38474195, 2024). "Cellular molecules linked to cancer development, such as vascular endothelial growth factor (VEGF) and glucose transporter 1 (GLUT-1), are regulated by HIF-1α activity." (PMID 38792080, 2024). "Further, the mRNA expression level of HIF1A was found to be positively correlated with mRNA expression PD‐L1 (CD274) in a variety of cancer types in the TCGA cancer patient dataset." (PMID 38956900, 2024). "HIF-1α is an oxygen-sensitive transcription factor that plays a crucial role in various cancers including HNCs." (PMID 39684225, 2024). "Hypoxia is an essential factor in cancer development, and this effect was related to the activation of downstream genes that are subject to HIF-1α." (PMID 38697993, 2024). "HIF-1α can increase the invasiveness of cancer cells, promote metastatic spread and radio resistance." (PMID 38474362, 2024). "HIF-1α is known to influence various factors that contribute to intravasation—the process by which cancer cells enter blood vessels." (PMID 38399410, 2024). "The Cancer Genome Atlas database revealed that lung cancer tissues had elevated expression levels of HIF1α and HIF2α." (PMID 39547513, 2024). "HIF-1α is highly expressed in GC cells and it has been reported that miR-576-3p can regulate HIF-1α expression in cancer." (PMID 39816354, 2024). "With a deeper understanding of lncRNAs, their role in regulating HIF-1α under both hypoxic and normoxic conditions in cancer has garnered attention." (PMID 39108268, 2024). "Emodin inhibited HIF-1α expression in five human pancreatic cancer cell lines, as well as attenuating cancer cachexia in in vivo models." (PMID 38667760, 2024). "This hypoxia‐selective release of AZD6738 inhibited ATR activation (T1989 and S428 phosphorylation) and subsequently abrogated HIF1a‐mediated adaptation of hypoxic cancers cells, thus selectively inducing cell death in 2D and 3D cancer models." (PMID 38976561, 2024). "Through its influence, HIF-1α facilitates the adaptation of cancer cells to low oxygen and nutrient availability." (PMID 39493156, 2024). "Downregulated genes were primarily hypermethylated in S1-10 and S1-32 treatment groups and have roles in HIF1a signaling, senescence, cancer, and adipogenesis." (PMID 38764585, 2024).
cancer (continued). "HIF1A (Hypoxia inducible factor 1A) is one of the influential external carcinogenic factors in the expression of PD-L1 and has a novel role in cancer target therapy such as immunotherapy." (PMID 38462658, 2024). "The HIF-1α plays a key role in cancer cell metastasis and drug resistance, which is an important factor limiting the response of many cancers to chemotherapy." (PMID 38188151, 2024). "HIF-1α induces the expression of many genes related to cancer cell growth and survival, angiogenesis, metastasis, cancer metabolism, cancer stem cell maintenance, and resistance to cancer treatment modalities." (PMID 38892084, 2024). "In conclusion, our research elucidates the mechanism of MYH9 and the p-MYH9 /USP22/HIF-1α axis in promoting cancer stemness and LR in HCC." (PMID 39300073, 2024). "Researchers have discovered that the mRNA and protein expressions of HIF-1α are undetectable in most normal tissues, but overexpressed in a variety of human cancers, and HIF-1α exacerbates tumorigenesis, metastasis, and angiogenesis." (PMID 38376551, 2024). "In cancer cells, the application of 55 (1 μM, dark) decreased the protein levels of HIF-1α and PD-L1 (repressor of T cells) via activation of 5’ AMP-activated protein kinase." (PMID 39138299, 2024). "Cancer cells are known to induce the activation of HIF-1α under hypoxic conditions, leading to the upregulation of glycolysis-associated proteins like GLUT-1, thereby facilitating the sustenance of the glycolytic pathway." (PMID 38792080, 2024). "SMURF2’s role in modulating HIF1α stability further underscores its potential as a therapeutic target in cancer." (PMID 39697237, 2024). "Epithelial-mesenchymal transition (EMT): The EMT, which is facilitated by HIF-1α, increases the migratory and invasive potential of cancer cells." (PMID 39493156, 2024). "The HIF-1α controls various processes of cancer cells including cell growth, proliferation, invasion, apoptosis, and autophagy." (PMID 39167288, 2024). "MiR-212 is regulated by nuclear factor IA (NFIA) and hypoxia-inducible factor-1α (HIF-1α) and has been identified as a potential biomarker for cancer diagnosis and treatment." (PMID 39062744, 2024). "This mechanistic explanation offers valuable insights into the degradation pathways and reveals alternative approaches for the targeted therapeutic intervention of HIF-1α in cancer." (PMID 38399410, 2024). "Gal-3 overexpression was observed in hypoxic fields of cancer tissues, in this regard; the relationship between HIF-1a and Gal-3 in oral carcinogenesis was recently investigated." (PMID 38951854, 2024). "The regulation of GLUT5 by HIF1α is not limited to specific cancer types but represents a more general phenomenon of metabolic adaptation to hypoxia." (PMID 39107723, 2024). "The Cancer Genome Atlas data has shown that its expression level is higher in glioblastoma tissues than in normal tissues, and high expression of HIF-1α was found to result in shorter disease-free survival and overall survival." (PMID 38188151, 2024). "As disrupting glycolysis, all these inhibitors target the critical element of the metabolism in cancer cells that is regulated by HIF-1α." (PMID 39493156, 2024). "Under hypoxic conditions, HIF-1α promotes a shift towards anaerobic glycolysis by increasing the transcription of genes involved in glucose transport and glycolysis, which supports cancer cell survival in low-oxygen environments." (PMID 39408832, 2024). "Thus, inappropriate HIF-1α signaling results in dysplasia caused by collagen overmodification, an effect that may also contribute to other extracellular matrix-related diseases such as cancer and fibrosis." (PMID 38198812, 2024).
cancer (continued). "By analyzing TOR1B's interaction with metabolic pathways and its regulation by HIF-1α, we identified it as a key player in cancer cell adaptation to hypoxia." (PMID 38842687, 2024). "HIF1α was shown to mediate stemness in cancer cells, so what would be the role of NFκB in general, if it is upstream of HIF1?" (PMID 39201306, 2024). "As ascorbic acid availability is lowered by the altered NADP+/NADPH ratios in IDH mutant cancers, it should also be noted that ascorbate encourages hydroxylase activity to suppress the transcriptional response of HIF-1α." (PMID 39596840, 2024). "This interaction suggests that SMURF2 is not only a regulator of HIF1α but also a potential therapeutic target in cancers where hypoxia plays a critical role." (PMID 39697237, 2024). "IGF2BP3 and HIF-1α together affect cancer cell metastasis and neovascularization, while inhibiting their expression better inhibits adverse factors that accelerate tumor progression." (PMID 39033180, 2024). "First, although both HIF-1α and HIF-2α are involved in cancer progression, most inhibitors have targeted only HIF-1α." (PMID 38799423, 2024). "This aligns with recent studies delving into the function of HIF‐1α in cancer‐related symptoms and the exploration of targeted therapies." (PMID 38898772, 2024). "HIF1α enables cancer cells to thrive in the hypoxic conditions of the TME by regulating genes essential for survival, proliferation, and metabolic adaptation." (PMID 39697237, 2024). "Our findings emphasize the significance of HIF-1α, VEGFa, NF-κB and Gal-1 signaling pathways in the implementation of novel treatment techniques against drug-resistant cancers; especially sorafenib-resistant ones." (PMID 39152108, 2024). "In cancer, HIF-1α is often upregulated not only due to hypoxic conditions but also through genetic alterations that stabilize and activate the protein regardless of oxygen levels." (PMID 39493156, 2024). "Since the protein level of HIF-1α is critical to cancer migration and invasion, we next investigated the effects of Pol ι downregulation on ESCC motility." (PMID 38402183, 2024). "In particular, the mechanism of action of IL-18 in cancer progression involves hypoxia, which induces the transcription and secretion of IL-18, followed by the expression of hypoxia-inducible factor-1α (HIF-1α)." (PMID 39451257, 2024). "Mitochondria-derived ROS can promote cancer initiation through oxidative stress and cancer cell progression via hypoxia-inducing factors, particularly HIF-1α." (PMID 38668357, 2024). "The high number of HIF-1α inhibitors reflects the extensive research performed in several fields including cancer, diabetes, ischemic and cardiovascular diseases, stroke, and inflammation." (PMID 39003252, 2024). "HIF-1α also drives metabolic reprogramming, shifting energy production from oxygen-reliant processes to glycolysis, enabling cancer cells to thrive in low-oxygen environments." (PMID 38842687, 2024). "The efficacy of nano-based therapy incorporating HIF-1α siRNA holds promise in overcoming cancer drug resistance." (PMID 39459028, 2024). "These organoids can thus be employed as an in vitro model for studying the effect of HIF-1A on cancer-related properties and for high-throughput screening of chemotherapeutic drugs." (PMID 39567394, 2024). "On the contrary, mir-21 induces the expression of SP1, MYC, and HIF1A and promotes cancer progression via the induction of immune-suppressive mechanisms." (PMID 39590335, 2024). "In solid tumors, elevated HIF1α orchestrates a metabolic shift from oxidative phosphorylation to glycolysis in order to supply the necessary energy to support cancer cell growth and function." (PMID 38339062, 2024). "The analysis showed that TWIST1, RUNX1, CEBPA, and RELA were upregulated in carcinoma samples compared with normal renal tissues, whereas HIF1A was downregulated." (PMID 38724670, 2024).
cancer (continued). "NNAs modifiedwith clinically validated antisense oligonucleotides (ASOs) that targethypoxia inducible factor 1-α (HIF-1-α) mRNA showed enhancedactivity compared with that of the soluble DNA across multiple celllines as well as a 3D cancer spheroid model." (PMID 37910400, 2023). "HIF1A facilitates cancer development through the promotion of glycolysis via activation of LDHA, a key glycolysis-related enzyme, and the content of LDHA was markedly reduced by M4N+TMZ combination treatment." (PMID 37228120, 2023). "Multiple studies have indicated that HIF1α expression is elevated in numerous malignancies and promotes cancer progression." (PMID 37894802, 2023). "The hypoxic microenvironment has shown to be a relevant mechanism on cancer progression and is mainly modulated by the HIF-1α, which has been closely related to development of drug resistance in HCC." (PMID 36376373, 2023). "Hypoxia and HIF-1α increase glucose channeling into aerobic glycolysis, which is what most cancer cells prefer." (PMID 37491250, 2023). "Another regulator for aerobic glycolysis in cancer cells is HIF1α, and this protein is positively enhanced by the activation of mTOR." (PMID 37259304, 2023). "Several studies have shown that HIF-1α upregulation in TNBC controls cancer metastasis, CSC self-renewal, and invasion." (PMID 37492478, 2023). "In order to adapt to such circumstances, cancer cells tend to retain high HIF-1α activities and gain malignancies." (PMID 36831085, 2023). "Intratumoral hypoxia causes reprogramming of energy metabolism, suppression of oxidative phosphorylation (OXPHOS), and promotion of glycolysis and lactate fermentation mediated by hypoxia-inducible factor 1 alpha (HIF-1α), which affects cancer cell properties." (PMID 37108667, 2023). "Hypoxia-inducible factor 1α (HIF1α) is a transcription factor that regulates the cellular response to hypoxia and seems to be dysregulated in cancer cells." (PMID 37174978, 2023). "In line with our results, HIF1A has been proposed as an effective biomarker for response to immunotherapy and as a cancer suppressor gene in ccRCC." (PMID 38067341, 2023). "Both the suppression of HIF-1 activity by zinc(II) supplementation and the targeted knockdown of HIF-1α expression by siRNA significantly enhanced chemosensitivity in cancer cells and suppressed chemoresistant xenograft tumor growth in vivo." (PMID 37345014, 2023). "It is important to mention that constitutive HIF-1α signaling also maintains the effector function of T cells during chronic viral infection and cancer." (PMID 37891230, 2023). "Once activated, mTOR affects the translation of oncogenic and angiogenic proteins (including HIF-1α), thus supporting cancer progression." (PMID 38273861, 2023). "In particular, high levels of HIF-1α expression are often found in various types of cancers because of efficient consumption of oxygen and dysfunctional vascularization in cancers." (PMID 37615898, 2023). "Hypoxic environments and subsequent activation of hypoxia-inducible factor 1α (HIF1α) are common features of advanced cancers." (PMID 36764954, 2023). "Notch signaling is up-regulated and collaborates with Hif-1a to promote downstream gene expression such as Hes and Hey genes under hypoxia as reported in cancer cells." (PMID 36726165, 2023). "To investigate the connection between hypoxia and COZP1, we analyzed the correlation of COPZ1 and HIF1A as well as the LOXL2 in 33 cancer types." (PMID 37107648, 2023). "Significant correlations were observed between HIF-1α and the cancer cell fraction, TAM fraction, CAMF fraction, and CTL/Treg ratio." (PMID 38012636, 2023). "The role of HIF-1α in the pathomechanisms of various cancers is well-documented and encompasses many facets of cancer biology." (PMID 38140111, 2023). "In preclinical studies using human cancer cell lines, it was demonstrated that arginine deprivation therapy reduces HIF-1α and HIF-2α protein levels." (PMID 37445845, 2023).
cancer (continued). "Cancer models have pointed to HIF-dependent mechanisms such as the physical interaction between ERRα/HIF-1α, as well as HIF-independent mechanisms such as direct VEGF modulation by ERRα." (PMID 37175690, 2023). "In recent years, considerable attention has been focused on unraveling the complex role of HiF-1α in the context of cancer." (PMID 38063756, 2023). "PI3K/Akt/mTOR signaling pathway is therefore one of the major alternate pathways through which upstream regulators such as CD147 modulate HIF-1α expression and function resulting in adaptive angiogenesis and metabolic reprogramming exhibited by cancers." (PMID 38023152, 2023). "It has been reported that metformin also blocks HIF-1α accumulation through suppression of the mTOR pathway in different types of cancer." (PMID 37760498, 2023). "The cancer-promoting transcription factor HIF-1α is a heterodimeric protein and consists of an oxygen-controlled α-chain and a constant β-chain." (PMID 37583906, 2023). "HIF-1α-mediated PDK1 activation results in the preference of cancer cells towards aerobic glycolysis." (PMID 37759534, 2023). "HIF-1α reprograms cell metabolism such that the cancer cells shift from oxidative phosphorylation to glycolytic metabolism (Warburg effect), guarantying survival despite a limited source of oxygen in the microenvironment." (PMID 36846589, 2023). "Further, lactate production by glycolytic cancer cells can induce the upregulation of HIF-1α in TAMs to enhance the expression of glycolytic genes and M2-like state." (PMID 37740232, 2023). "In turn, the activity of E3 ubiquitin ligases decreases, which results in elevated HIF1α expression, leading to increased cancer progression and metastasis." (PMID 37583933, 2023). "On one hand, this idea seems counterintuitive, as BACH1 has been suggested to repress angiogenesis and VitC was found to reduce HIF1α levels and target gene expression in some cancer cell lines." (PMID 37651203, 2023). "The relative XIST expression level in serum was detected using U6 as a standard and was positively correlated with HIF-1a expression levels in cancer tissues (P<0.001)." (PMID 37036874, 2023). "During hypoxia, lncRNA-CF129145.1 expression in PDAC cancer cells is suppressed by the HIF-1α/HDAC complex." (PMID 37444595, 2023). "HIF-1α plays a critical role in glycolytic metabolism through upregulating glycolysis-related enzymes in cancer cells." (PMID 38098117, 2023). "The analysis revealed that the GBM CAF secretome upregulated cancer progression pathways, including HIF-1α, EMT, and cell proliferation in GSCs." (PMID 36856115, 2023). "In fact, HIF-1α is widely expressed and related to the poor prognosis of human cancer by regulating glycolysis, angiogenesis, cell cycle progression and cell pathways 22-25." (PMID 37781511, 2023). "Hypoxia-inducible factor 1 subunit alpha (HIF1A) is a transcription factor that helps cancer cells adapt to hypoxic conditions." (PMID 37716978, 2023). "HIF-1α is a common link between adaptation to hypoxia, changes in cancer metabolism, and cancer progression." (PMID 37540301, 2023). "The expression of HIF-1α in HCC SK-Hep1 cells co-cultured with NK-92 cells decreased the expression of apoptotic molecules in cancer cells." (PMID 37501379, 2023). "Metabolic reprogramming is not only regulated by factors such as HIF-1α, but also by dysregulation of certain signaling pathways that also contribute to cancer metabolic remodeling." (PMID 36594102, 2023). "Extensive study on the stability of HIF-1α under conditions of acute hypoxia in cancer progression has been conducted, however, understanding of its involvement during the chronic phase is limited." (PMID 37777750, 2023). "Given that hypoxia is a common feature of many solid tumors, HIF-1α is frequently activated in cancer cells." (PMID 38138162, 2023).